ESR1 (estrogen receptor 1)
Diseases named in the same sentence as ESR1 in open-access papers (continued):
Sharing a sentence is not in itself a finding about the gene and the disease.
cancer (continued). "For each ESR1-expressing clone, the peak fluorescence values are found largely within a similar z-range as the hepatocytes, indicating that the cancer cells are primarily found infiltrating within the hepatocyte layer." (PMID 31171849, 2019). "To quantify cancer cell growth within our models, we next calibrated the imaging platform by quantifying fluorescence intensity of the respective ESR1 expressing cell lines over a 700-fold range of cell densities (200–140,000 cells)." (PMID 31171849, 2019). "E380Q mutations gather outside ESR1 LBD hotspot cluster sites, and exhibit a yet-to-be-understood mechanism of cancer proliferation different to that of the constitutive activation identified in Y537S and D538G mutants." (PMID 31795152, 2019). "Using confocal analysis to generate 3D renderings for each ESR1 clone (WT, Y537S, D538G) we observe a similar spatial distribution between the hepatocyte layer and the ESR1-expressing cancer cells in LAMPS models." (PMID 31171849, 2019). "The goal is to enhance our understanding of the reciprocal relationship between ESR1 LBD mutations and the liver metastatic microenvironment, a common metastatic site for numerous types of cancer, including MBC." (PMID 31171849, 2019). "In fact, we previously showed that DNA hypermethylation of the ESR1 promoter occurred only in cancer tissues and that this region remained hypomethylated in non-cancer tissues regardless of the ESR1 expression level." (PMID 30728052, 2019). "And we found that one TF, E2F3 was related to ESCA, two genes, DTNA and KCNMA1 were related to STAD, while one TF ESR1 and one gene KIT were associated with both of the two types of cancer." (PMID 31888440, 2019). "NFE2L2 silencing showed a higher expression of ESR1 in the NFE2L2-downregulated cancer cell lines OVCAR3 (p = 0.003) and ES2 (p < 0.001)." (PMID 30597961, 2018). "Silencing of NFE2L2 induced a higher mRNA expression of ESR1 in the NFE2L2 downregulated cancer cell lines OVCAR3 (p = 0.003) and ES2 (p < 0.001), confirming genetic interactions of NRF2 and ERα." (PMID 30597961, 2018). "IRE1/XBP1 has been shown to confer resistance to doxorubicin and paclitaxel in TNBC and to tamoxifen in ESR1+ cancers." (PMID 30248920, 2018). "Epidemiological and experimental evidence show that estrogen (17β-estradiol; E2) promotes ovarian tumorigenesis and cancer progression predominantly through the estrogen receptor ESR1." (PMID 29973689, 2018). "When the 16 cancer-related genes of the test were analyzed separately, the ESR1 transcript level was highly predictive of adjuvant tamoxifen benefit, while the MKI67 transcript level, encoding the Ki67 protein, was not." (PMID 30041599, 2018). "Since several studies have identified this miRNA to be a regulator of ESR1 in these cancer types, we evaluated miR-18a-5p functional contexts in the decodeRNA output." (PMID 29220434, 2017). "The impact on survival was similar to that observed with increased estrogen receptor-1 (ESR1) expression, a marker of more differentiated cancers." (PMID 28583174, 2017). "The findings of our study show that TH and MH showed a lowering effect on E2 concentration at serum level and ESR1 at cancer tissues level." (PMID 28479926, 2017). "The results suggest that ESR1-mutant cancers show selective sensitivity to fulvestrant, a drug that degrades the ER, in comparison to AIs." (PMID 28361033, 2017). "TH treatment groups were found to have a lower anti-apoptotic proteins (E2, ESR1 and Bcl-xL) expression and a higher pro-apoptotic proteins (Apaf-1 and Caspase-9) expression at serum and on cancer tissue level (p < 0.05)." (PMID 28399853, 2017). "Of the aDNAm’s identified, 650 are known to be involved in cancer, including ESR1 and beta-estradiol responsive genes." (PMID 29383109, 2017).
cancer (continued). "Our aim was to investigate how CTC derived gene expression of treatment predictive markers (ESR1/HER2) and other cancer associated markers changed in patient blood samples during six months of first-line systemic treatment for MBC." (PMID 28489591, 2017). "Increased references in PubMed also provided us other hub proteins involved in cancer pathways, such as ESR1, PTEN, BCL2, AR and MAPK3." (PMID 27917343, 2016). "Somatic mutation in cancer based on copy number, aberrations, nucleotide substitutions, and on subsets in breast cancer BRCA1/2 are found by dGene, DGIdb HER2, and ESR1 estrogen receptor (ER) gene mutations for finding a drug or kinase inhibitor." (PMID 26973813, 2016). "The relationship among expression of ESR1, HLAs, and IFN-associated molecules was analyzed from The Cancer Genome Atlas (TCGA) and Cancer Cell Line Encyclopedia (CCLE) data." (PMID 27121061, 2016). "Conversely, we delineate that ESR1-responsive enhancer hypomethylation is critical in transition from normal mammary epithelial cells to endocrine-responsive ESR1-positive cancer." (PMID 26169690, 2015). "Functional annotation of the new three classes of ESR1 target genes by DAVID tool revealed that 'A' genes are highly enriched in pathways active in cancer, including the MAPK signaling pathway." (PMID 26099425, 2015). "Two other genes (BRCA1 and ESR1) displayed very small changes in the extent of methylation (<2 % differential for cancer vs. adjacent tissue)." (PMID 26510686, 2015). "Another study showed that rs4784227 are enriched in the cistromes of FOXA1 and ESR1 in a cancer-cell specific manner, modulating the affinity of chromatin for FOXA1 and resulting in allele-specific gene expression." (PMID 25531440, 2014). "ESR1 has been used not only for diagnosis but also as a molecular target to treat cancer patients with this subtype." (PMID 23666744, 2013). "This is supported by far higher overlap of ESR1 ChIP-seq peaks in primary cancer cells with cell line ChIP peaks found in multiple datasets." (PMID 24171864, 2013). "In cancer cells, pRb modulates the activity of the AR and ESR1, the two principal determinants of hormonal cancer." (PMID 23900261, 2013). "Integration of multiple cell line ESR1 ChIP datasets also increases overlap with ESR1 ChIP-seq peaks from primary cancer samples, further supporting this approach as helpful in identifying true positive ESR1 binding sites in cell line systems." (PMID 24171864, 2013). "AP2α was indeed found to interact with the predicted sites on the GAS2 and on KLK-5 upstream regulatory sequences in the cancer cells as well as to the AP2α binding site in the promoter of the estrogene receptor gene used as a positive control (ESR1)." (PMID 21876733, 2011). "Our results have shown, for the first time, a correlation between hypermethylation of CXCL12 island 4 and ESR1 in patients with histologically advanced cancer, the presence of metastases and death." (PMID 20109227, 2010). "Clarifying which ESR1 fusions act as true oncogenic drivers versus incidental events will be critical for refining diagnostics and informing future therapeutic development for oncofusion-driven cancers." (PMID 42135449, 2026). "This study highlights how nanomaterial-induced ESR1 activation can lead to enhanced epithelial-mesenchymal transition and cell cycle progression, suggesting potential adverse effects of nanomaterials in ER+ cancer proliferation via protein kinase-mediated ESR1 modulation." (PMID 41345200, 2025).
cancer (continued). "For example, in TCGA-BRCA, ESR1 is altered by mutation or expression in ∼10% of tumors, whereas other NRs (eg, NR5A2/LRH-1, ESRRG, NR1I3/CAR) are more frequently altered, and only a handful of cistromic datasets exist for these receptors across all cancers." (PMID 41150850, 2025). "Our observations on CAP enhancement of estradiol binding to the ESR1 predict two previously unsuspected mechanisms by which CAP may influence cancer cell growth." (PMID 40003617, 2025). "Core nodes include IL6, MYC, VEGFA, EGFR, and ESR1, all of which play essential roles in cancer development and may act as critical molecular regulatory hubs." (PMID 40045358, 2025). "In these cancers, ESR1’s promoter is hypermethylated and therefore underexpressed." (PMID 40790102, 2025). "One is the enhancement of estrogen binding to the ESR1 which, acutely, may stimulate estrogen-sensitive cancers but chronically and at higher CAP dosages would likely downregulate ESR1 expression, thus producing a tamoxifen-like effect." (PMID 40003617, 2025). "This phenomenon may be attributed to the fact that ESR1+ patients exhibit significant responsiveness to tamoxifen, and cancer women with ESR1 amplification showed significantly prolonged survival following adjuvant tamoxifen monotherapy." (PMID 41155171, 2025). "Conclusions need to be derived from combinations of different models and the community has been proactive about sharing resources and insight to reach clinically meaningful conclusions and new treatment strategies have subsequently been devised for patients with mutant ESR1 cancers." (PMID 40265613, 2025). "It exerts this effect by stabilizing the ESR1 mRNA through competition for binding with miR-181a-2-3p, hence leading to an increase in the level of the ERα protein and subsequently activating target genes that are required for cancer cell growth and survival." (PMID 40740236, 2025). "Within our setting, elacestrant or other treatment options for ESR1 mutated cancer cases were not yet approved in Germany." (PMID 39839709, 2025). "The binding of capsaicin to the ESR1 may also enhance ESR1 antagonists such as tamoxifen, benefiting some cancer patients." (PMID 40003617, 2025). "Trans-cinnamate demonstrated strong binding affinities for SRC and ESR1 (-8.5 kcal/mol), suggesting that trans-cinnamate may promote cancer cell death through modulation of key signaling pathways involved in cell survival and apoptosis." (PMID 40877012, 2025). "PIWIL1 mediates the ERα signaling pathway involved in E2-stimulated carcinoma cell proliferation, which may be one of the mechanisms by which ESR1 methylation contributes to EC progression." (PMID 39781343, 2025). "Finally, we investigate the role of intrinsically disordered regions within the key cancer-related TF ESR1 in DNA binding and transcriptional activity, and found that these regions can have complex trade-offs in TF function." (PMID 39013578, 2024). "Interestingly, in a recent multisample, whole-genome analysis, ESR1 amplification was observed during the transition of cancer cells to metastatic CRPC, supporting our results." (PMID 38625747, 2024). "Stenotrophomonas, an opportunistic pathogen with increased colonization/infection in cancer patients, exhibited extensive positive associations with the hypermethylation of genes, including multiple TSGs in CRC, such as ESR1, RASSF5, DIRAS1, CADM1, ST5, GJB2, FAM172A, and HIVEP3." (PMID 38840170, 2024). "Furthermore, this study extends the knowledge of DNA methylation control over ESR1 gene expression in the context of BRCA1-like cancers, as reported for a limited set of CpGs in the seminal work of Archey and coworkers." (PMID 37373065, 2023).
cancer (continued). "Although our qPCR analysis detected the expression of isoform 1, 2, and 4, while Western blotting and IHC recognized ERα1, ERα2, and ERα3, we saw the same trend of statistically decreased levels of ESR1 mRNA and ERα protein in cancer tissue compared to adjacent control tissue." (PMID 36769338, 2023). "In our meta-analysis, we identified six genes with high mutation prevalence in brain metastases, of particular interest for their potential role in brain metastatic process and resistance to first-line anti-cancer drugs: ESR1, ERBB2, EGFR, PTEN, BRCA2 and NOTCH1." (PMID 36980614, 2023). "Besides its well-known role in BC cancer management, the discovery that ESR1 was localized in brain regions considered to be involved in Mi pathogenesis suggested the role of ER in Mi development as well." (PMID 37371707, 2023). "In addition, gene network analysis regarding to mass-type ER-positive cancers showed that ESR1, BIRC5, CAV1, FGFR1, IL6, MIR27, and PTTG1 were upregulated." (PMID 37391754, 2023). "Restoration of expression of genes such as ESR1 or PITX2 sensitizes cancer cells to tamoxifen, and the analysis of promoter methylation status of these genes enables the identification of patients with positive expression of the hormone receptor that will not benefit from the drug administration." (PMID 37108398, 2023). "ESR1 has been established as a promoter of cancer in breast and the female reproductive system." (PMID 37900162, 2023). "By searching and analyzing GO, KEGG, and GSEA databases, we identified enriched cellular components and pathways tightly associated with cell junctions and adhesions, suggesting that ESR1 methylation might promote cancer metastasis." (PMID 37881785, 2023). "It is generally believed that ESR1 regulated the expression of protein-coding genes closely related to cell proliferation, survival, differentiation, and participation in the process of cancer (Hu, Chen & Ding, 2018)." (PMID 35411258, 2022). "Previous studies have shown that DNA methylation may silence the promoter of ESR1 in several cancers." (PMID 35162942, 2022). "The fusion between ESR1 and its neighboring gene CCDC170 are potentially generated by tandem duplication, which is also causing other genetic rearrangements in cancer." (PMID 35151276, 2022). "Furthermore, this case displayed inter‐CTC heterogeneity of the ESR1 mutation, with a combination of biallelic and monoallelic mutant as well as ESR1 wild‐type cancer cells present in circulation." (PMID 34866317, 2022). "Cancers develop resistance to these forms of therapy over time, often through alterations in the ESR1 gene including activating point mutations in the ligand binding domain and gene fusions that restore ERα transcriptional activity." (PMID 35999225, 2022). "There were two common proteins (EGFR and ESR1) that had DIHCP features in all cancers studied." (PMID 36422095, 2022). "In addition, this draws attention to the decreasing strength of the ESR1 correlation, which was the highest in unchanged tissue and the lowest in cancer tissue samples in the case of all analyzed ESR1 ratios." (PMID 34207568, 2021). "Many TFs, such as FOXA1 and ESR1, have been shown to function in a context-specific manner, dependent on specific protein–protein interactions, resulting in pro-oncogenic properties in some cancer types, and anti-oncogenic properties in others." (PMID 33850167, 2021). "Taken together, these data suggest that ESR1 mutations in the LBD maintain the ERα-driven transcriptional program within these cancer cells, even in the absence of estrogenic ligand; thus contributing to endocrine resistance." (PMID 34528025, 2021). "Downregulation of expression of ESR1 by Rhodiola and other adaptogens may be effective for preventing and treating some aging‐related cancers such as breast cancer, ovarian, colon, prostate, and endometrial cancers." (PMID 33103257, 2021).
cancer (continued). "Interestingly, the gene set enrichment analysis highlights an enrichment corresponding to the upregulation of genes upon inhibition of ESR1 and response to endocrine therapy in cancer." (PMID 34635729, 2021). "A small number of hypoxia-associated genes (APLN, HIF1A, and BNIP3), cancer stem cell (CSC) markers (CD24 and CD44), hormonal regulation (HR) genes (ESR1, PGR, and TFF1), other selected genes (PPARGC1A, ILK), and HKGs (RPL32, GUSB, TBP, OAZ1 and NONO) were also included in the panel." (PMID 34206049, 2021). "ESR1 and AR are the morphogenetic factors that regulate cell proliferation, differentiation, angiogenesis, and the development of some tumors, which were predicted to link the Epimedium to cancer with highest scores." (PMID 33460401, 2021). "Furthermore, a negative correlation between mRNA expression of the estrogen receptor 1 (ESR1) gene and HLA was also found in the Cancer Cell Line Encyclopedia (CCLE)." (PMID 34135901, 2021). "Here, we explore some of the top ranked TRs including histone deacetylase 2 (HDAC2), estrogen receptor 1 (ESR1), TEA domain family member 4 (TEAD4), achaete-scute homolog 1 (ASCL1), androgen receptor (AR) and yes associated protein 1 (YAP1) in several cancer types." (PMID 33778495, 2021). "The genes preferentially mutated in metastases were MYLK, PEAK1, SLC2A4RG, EVC2, XIRP2, PALB2, and ESR1 (five of which are not significantly mutated in any type of human primary cancer)." (PMID 34771579, 2021). "Therefore, we used the cBioPortal web tool for further analysis of the genetic mutations in ESR1, ESR2, and PGR in multiple cancer types." (PMID 34322374, 2021). "Finally, NDRG1, also significantly upregulated in ESR1-depleted recurrences and generally expressed in basal cancers, showed differential expression in three distinct LTED cell lines." (PMID 33407744, 2021). "To inquiry genetic alterations of ESR1, ESR2, and PGR that may be associated with tumorigenesis, we analyzed these in pan-cancer involving a total of 10,189 patients." (PMID 34322374, 2021). "Furthermore, we discovered that some of the predicted target genes of Oroxylum indicum were associated with cancer, such as EGFR, PIM1, ESR1/2, and MAPK8/10." (PMID 32733583, 2020). "A recent study showed that ESR1-LDB mutations, in addition to promoting ligand-independent growth, also promote a more aggressive phenotype, leading to changes in ER transcriptional network that mediate cancer progression." (PMID 32210163, 2020). "Another example is ESR1, in which case the paralogs were born at the level of eumetazoa; however, this event is not directly linked to the emergence of the cancer region, which appeared only at the level of the ancient vertebrates." (PMID 32731489, 2020). "Estrogen receptor α (ESR1) plays a critical role in promoting growth of various cancers." (PMID 32513126, 2020). "Furthermore, genetic silencing or chemical inhibition of menin has been shown to reduce proliferation of ER+ breast cancer cell lines via down-regulation of a cancer-specific gene expression program including the estrogen receptor gene (ESR1) itself." (PMID 31947537, 2020). "Interestingly we also report a second ESR1 D538G mutation at 32% cancer cell fraction (CCF) in Ovary Met R2, indicating that strong selective pressures and consequent convergent evolution for ESR1 mutants." (PMID 32221288, 2020). "ESR1 mutations occur within the LBD sequence, and are rare in primary cancer." (PMID 31231679, 2019). "Moreover, ESR1 and ZNF423 have a role in cancer cell proliferation and were significantly associated with platinum-sensitive tumors." (PMID 31554806, 2019).